NLRP3 (NLR family pyrin domain containing 3)
Diseases named in the same sentence as NLRP3 in open-access papers (continued):
Sharing a sentence is not in itself a finding about the gene and the disease.
Sepsis (continued). "Zhang’s group identified NLRP3 as a potential therapeutic target for sepsis-induced ALI." (PMID 38675431, 2024). "It is speculated that this may be related to the involvement of NLRP3 and IL‐18 in the process of sepsis." (PMID 39692606, 2024). "Interestingly, SYK takes part in TLR4 signaling, and in the activation of the NF-κB pathway and the NLRP3 inflammasome, which are known to be crucial players in the pathophysiology of sepsis." (PMID 39559354, 2024). "Additionally, Tangeretin mitigates sepsis‐induced ALI by inhibiting ROS‐mediated NLRP3 infammasome activation by influencing the PLK1/AMPK/DRP1 signalling axis." (PMID 39623879, 2024). "Similarly, the NLRP3 inflammasome mediates the onset of numerous inflammatory diseases, including sepsis-induced septic shock." (PMID 39234245, 2024). "Many studies have reported the effect of the NLRP3 inflammasome on the pathogenesis of sepsis." (PMID 37650025, 2023). "Furthermore, NAC is capable of regulating the NLRP3 inflammatory vesicle activation for the treatment of diseases, including aortic aneurysms, sepsis to inhibit NLRP3 inflammatory vesicle activation." (PMID 37556466, 2023). "Serum NLRP3 concentration has clinical value in the diagnosis of sepsis complicated with ARDS." (PMID 37649483, 2023). "Li showed that in LPS‐induced sepsis mice, STING‐IRF3 could activate the apoptosis and pyroptosis of cardiomyocytes by activating NLRP3 in mice, thus causing cardiac dysfunction." (PMID 37904696, 2023). "Further, we found that Plantainoside D (PD), an effective component of Plantago asiatica L could improve sepsis ALI by regulating Sirt3/NLRP3 pathway related proteins." (PMID 37494665, 2023). "Additionally, emodin attenuates inflammation and pyroptosis by inactivating methyltransferase‐like 3‐mediated NLRP3 in a cell model of sepsis brain injury." (PMID 36751097, 2023). "Moreover, in a recent report, PD was demonstrated to protect against mitochondrial dysfunction and NLRP3 inflammasome activation in sepsis-induced acute kidney injury by activating Parkin-dependent mitophagy via the activation of sirtuin 1 (SIRT1)." (PMID 37112536, 2023). "Therefore, targeting NLRP3 inflammasome activation and the subsequent pyroptosis would be a critical for the therapy of sepsis." (PMID 36923408, 2023). "The NLRP3 inflammasome complex, consisting of NLRP3, apoptosis-associated speck-like protein containing CARD (ASC) and caspase-1, plays a fundamental role in dysfunctional endothelium during sepsis." (PMID 37587410, 2023). "The NLRP3 inflammasome plays a crucial role in the mechanism of pyroptosis in sepsis." (PMID 38161332, 2023). "Previous studies have proven that NLRP3 facilitates the inflammatory response in sepsis." (PMID 37759588, 2023). "Notably, previous studies have shown that dysregulation of NLRP3 is involved in the pathogenesis of sepsis." (PMID 37649483, 2023). "Moreover, HSF1 can regulate the innate immunity of the NLRP3 inflammasome, leading to the protection of sepsis." (PMID 36741074, 2023). "The role of NLRP3 inflammasome in myocardial dysfunction in sepsis deserves further exploration." (PMID 37904696, 2023). "Studies have found NLRP3 inflammatory corpuscles as one of the targets for the treatment of sepsis." (PMID 37249295, 2023). "Moreover, NLRP3 inflammasome-mediated pyroptosis can also impact autophagy during sepsis development." (PMID 38161332, 2023). "In addition, serum NLRP3 concentrations of sepsis patients with pulmonary infection (pneumonia with or without ARDS) were significantly elevated (p<0.01)." (PMID 37649483, 2023). "In this study, the best critical value of NLRP3 diagnosis of ARDS in sepsis patients is 4.29 ng/ml, the sensitivity is 76.00%, and the specificity is 74.67%, which suggests that the abnormal elevation of NLRP3 level has certain warning significance to ARDS in sepsis patients." (PMID 37649483, 2023).
Sepsis (continued). "This further indicated that DP could inhibit the activation of the NLRP3 inflammasome in vivo and had a protective effect against sepsis in mice." (PMID 37859535, 2023). "The NF-κB signaling pathway and its subsequent activation of NLRP3 inflammasome may be an important immune mechanism for ARDS induced by sepsis." (PMID 38035100, 2023). "Although serum NLRP3 has potential for diagnosing and predicting prognosis in sepsis, its clinical application is still in its infancy, and it remains uncertain whether it will eventually be adopted as a standard biomarker in clinical practice." (PMID 37649483, 2023). "WWP1 might also contribute to YTHDF1-mediated alleviation of sepsis by promoting NLRP3 ubiquitination." (PMID 38129384, 2023). "Accumulating studies have suggested that serum levels of NLRP3 may have potential clinical applications in sepsis patient diagnosis." (PMID 37649483, 2023). "During sepsis, ATP activates the P2 × 7 receptor and NLRP3 signal transduction in an autocrine manner after activation of the inflammasome, leading to changes in metabolic status and convergence of inflammasome signals and is associated with increased lethality." (PMID 38020710, 2023). "Sepsis triggers NLRP3 activation in cardiomyocytes and cardiac fibroblasts." (PMID 37596540, 2023). "Furthermore, rhodopsin has been shown to decline the expression of NLRP3 and GSDMD in myocardial tissues, suppressing the activation of the NLRP3 inflammasome and ultimately reducing septic myocardial injury in an LPS-induced sepsis model." (PMID 38161332, 2023). "In cases of sepsis, including bacterial sepsis and viral conditions like COVID-19 (coronavirus disease-2019), aberrant activation of the NLRP3 inflammasome has also been documented mostly through the measurement of increased plasmatic concentrations of IL-1β and IL-18." (PMID 38140660, 2023). "It was found that NLRP3 inflammasomes are closely related to sepsis and SCM and can be involved in regulating SCM through cardiomyocyte inflammatory response and apoptosis, oxidative stress injury, calcium regulation, ERS, mitochondrial dysfunction, and exosomes." (PMID 37904696, 2023). "Notably, the global Nlrp3 knockout mouse was protected from sepsis and NLRP3 expression was shown to be essential in ATP-driven caspase-1 activity, and subsequent IL-1β secretion." (PMID 37622117, 2023). "Our data suggest that serum NLRP3 levels are significantly higher in sepsis patients complicated with ARDS and may be a potential biomarker for sepsis diagnosis and prognosis." (PMID 37649483, 2023). "This work explored the diagnostic value of serum NOD-like receptor family pyrin domain containing 3 (NLRP3) concentration in patients with sepsis for ARDS, and the predictive value of serum NLRP3 concentration at the time of diagnosis for death 28 days after treatment." (PMID 37649483, 2023). "Therefore, our data showed that PF reduced the release of pro-inflammatory monocytes by limiting the activation of the NLRP3 inflammasome, thereby alleviating the imbalance in the inflammatory response in patients with sepsis." (PMID 37650025, 2023). "Moreover, many studies have found that inhibiting the activation of the NLRP3 inflammasome reduces sepsis-induced acute lung damage and attenuates sepsis-induced acute kidney injury, and attenuates sepsis-induced acute kidney injury." (PMID 37650025, 2023). "Studies have shown that IMD could reduce the expression of major inflammatory factors in sepsis by regulating the NLRP3/Caspase-1/IL-1β pathway, thereby exerting a protective effect against sepsis-induced cardiac dysfunction." (PMID 37745233, 2023). "In this study, we explored whether the S1P receptors have a regulatory role in NLRP3 inflammasome activation and sepsis." (PMID 36798132, 2023).
Sepsis (continued). "miR-25-5p can improve brain injury caused by sepsis by inhibiting the thioredoxin-interacting protein TXNIP/NLRP3 pathway; reducing the levels of TXNIP, NLRP3, and cleaved caspase-1; and inhibiting the expression of inflammatory factors (such as IL-6, IL-1β, and TNF-α and peroxide)." (PMID 37629199, 2023). "NLRP3 inflammasome is widely considered to be ideal drug target for sepsis." (PMID 37359543, 2023). "Likewise, our previous study also confirmed that regulation of NLRP3 inflammasome activation can affect the occurrence and development of sepsis." (PMID 35847986, 2022). "The pieces of evidence presented here demonstrated that inhibiting the assembly and activation of this NLRP3 inflammasome could prevent the inflammatory response normally visualized in sepsis-related ALI." (PMID 35222388, 2022). "Furthermore, TWIK‐2 is required for sepsis‐induced NLRP3 inflammasome activation and inflammation in vivo." (PMID 35353387, 2022). "Accumulating evidence indicates that NLRP3-mediated pyroptosis results in plasma membrane rupture and subsequently in a drastic release of powerful proinflammatory factors such as IL-1β, thereby resulting in a hyperinflammatory response to sepsis." (PMID 35136484, 2022). "In addition, with the evolution of sepsis, there is a direction to the activation pathway of the NLRP3 inflammasome, becoming a cycle, culminating in the damage of the neuronal tissue generated by the deposit of 8-oxoG." (PMID 36333747, 2022). "We hypothesized that PPARγ inhibits overproduction of ROS by promoting Nrf2 expression to reduce NLRP3-mediated pyroptosis and alleviates sepsis-induced liver injury." (PMID 35136484, 2022). "Previous studies have revealed that NLRP3 inflammasome activation is responsible for pyroptosis of Kupffer cells, hepatic endothelial cells, and lung endothelial cells in SIRS/sepsis, which is associated with multiple organ dysfunctions and deteriorated prognosis." (PMID 35548710, 2022). "The activated NLRP3 inflammasome mediates the release of inflammatory factors and the occurrence of pyroptosis, and therefore is thought to play an important role in the development and progression of sepsis." (PMID 35847986, 2022). "In 2019, a study showed that Dexmedetomidine could reduce pyroptosis and histone release of astrocytes by reducing NLRP3 and caspase-1 recruitment in vivo and vitro, which might protect comprehensively nerve cells from damage in sepsis." (PMID 35572571, 2022). "1,2-diol may serve as a potential therapeutic drug and NLRP3 inflammasome signaling would be a novel pharmaceutical target for clinical treatment of sepsis-related ALI." (PMID 35222388, 2022). "Therefore, the NLRP3 inflammasome plays a key role in sepsis, and regulation of its activation can affect the progression of sepsis." (PMID 35847986, 2022). "Furthermore, NLRP3/IL-1β, MuRF1 and MAFbx expression were significantly increased in mice with lipopolysaccharide (LPS)-induced sepsis." (PMID 36405697, 2022). "Shikonin also prevented the activation of the NLRP3/caspase-1/IL-1β inflammasome pathway and increased the survival rate of Balb/c mice with LPS-induced lethal endotoxemia and caecal ligation and puncture–induced sepsis." (PMID 35637461, 2022). "Studies have highlighted the important role of NLRP3-mediated pyroptosis in sepsis." (PMID 35136484, 2022). "Furthermore, genetic deficiency of NLRP3 or caspase-1 abrogated the high mortality and disrupted liver interendothelial junctions caused by high dose of HNP-1 during sepsis." (PMID 35935811, 2022). "Additionally, NLRP3-dependent caspase-1/11-GSDMD pathway was previously demonstrated to mediate pyroptosis in the hippocampus of a sepsis model." (PMID 35508474, 2022).
Sepsis (continued). "The present study showed that TXNIP knockdown significantly inhibited hippocampal microglia activation in the sepsis mice, while the NLRP3 and cleaved caspase-1 protein expression levels and the inflammatory factors, IL-1β and IL-18, were significantly reduced in the hippocampus." (PMID 35571246, 2022). "This study clarified the regulatory role of YTHDF1 in sepsis with the involvement of WWP1/NLRP3/caspase-1 axis and found that YTHDF1 could upregulate WWP1 to enhance NLRP3 ubiquitination and restrict caspase-1-dependent pyroptosis in sepsis." (PMID 35508474, 2022). "Thus, the intraperitoneal administration of a high dose of HNP-1 induces liver endothelial NLRP3/caspase-1 inflammasome activation and subsequently destroys cell junctions, thereby increasing vascular permeability after sepsis onset." (PMID 35935811, 2022). "Further experiments have demonstrated that BBD can inhibit both the NF-κB pathway and assembly of the NLRP3 complex in peritoneal macrophages, suggesting that suppressing pyroptosis may be helpful in treating sepsis." (PMID 35967871, 2022). "Collectively, the 4-benzene-indol derivative may serve as a potential therapeutic drug and NLRP3 inflammasome signaling would be a novel pharmaceutical target for clinical treatment of sepsis-related ALI." (PMID 35222388, 2022). "Besides, it has been documented that NLRP3 inflammasome is critical in LPS‐induced sepsis and septic organ injury." (PMID 35548710, 2022). "Thus, Therefore, their subsequent studies found that IL-17A can activate NLRP3, which leads to pyroptosis in pneumonia-induced sepsis." (PMID 36349316, 2022). "Thus, the real impact of the NLRP3 inflammasome on platelets remains to be further characterized in sepsis." (PMID 35563812, 2022). "In addition, upregulated PPARγ inhibited the expression of the TXNIP/NLRP3 signaling pathway by reducing ROS-induced injury in the liver during sepsis, which further reduced NLRP3-mediated pyroptosis and the inflammatory response." (PMID 35136484, 2022). "In addition, excessive expression of NLRP3 were more obvious in macrophages from Card9−/−-sepsis mice compared with WT-sepsis mice." (PMID 35618701, 2022). "Similarly, in sepsis-induced acute lung injury, the knockdown of geranylgeranyl pyrophosphate synthase large subunit 1 was found to attenuate injury by suppressing NLRP3 inflammasome activity through the promotion of autophagy." (PMID 35967871, 2022). "The interaction of mitophagy and NLRP3 inflammasome may be a conceivable therapeutic strategy in the treatment of sepsis." (PMID 34837343, 2022). "Activation of the NLRP3 inflammasome plays a further important role in sepsis." (PMID 35774785, 2022). "NLRP3 activation involves both priming and triggering signals, hence inhibiting the inflammasome provides beneficial effects for controlling the inflammatory response in sepsis." (PMID 35774785, 2022). "In sepsis, a mitochondrial dysfunction is an important event in NLRP3 inflammasome activation, as NLRP3 stimuli activate the mitochondrial OxPhos machinery to increase ROS and decrease mitochondrial membrane potential (mtΔΨ) and respiratory chain complex activity." (PMID 36333747, 2022). "In conclusion, treatment with 3PO could inhibit the NLRP3-induced pyroptosis, one of the primary cell death pathways in intestinal injury in sepsis." (PMID 36589684, 2022). "Syringaresinol ameliorated sepsis-induced cardiac dysfunction via the ER/SIRT1/NLRP3/GSDMD pathway." (PMID 35509275, 2022). "The data showed a marked upregulation in the expression levels of TXNIP, NLRP3, caspase-1, and IL-1β, suggesting that the NLRP3 inflammasome may contribute to liver dysfunction during sepsis." (PMID 35136484, 2022). "In animal models of sepsis-induced AKI, the expression levels of NLRP3, apoptosis-associated speck-like protein containing a CARD, and caspase-1 were upregulated, and renal injury was ameliorated by NLRP3 deficiency or caspase-1 inhibition." (PMID 35359999, 2022).
Sepsis (continued). "Up to the present, molecular mechanisms and related signaling pathways indicate that preventing the assembly and activation of NLRP3 inflammasome could reduce the inflammatory response in sepsis." (PMID 35222388, 2022). "Intriguingly, NLRP3 inflammasome-mediated pyroptosis regulates autophagy during sepsis." (PMID 35967871, 2022). "The effect of the NLRP3 inflammasome on sepsis brain injury has been preliminarily studied in the CLP-induced mouse model, but the role of its regulatory protein TXNIP in the sepsis brain injury and the effects on the NLRP3 inflammasome remain unknown." (PMID 35571246, 2022). "Finally, we confirmed HG exerts a protective effect against sepsis-induced ALI by inhibiting NF-κB pathway-modulated NLRP3 inflammasome activation." (PMID 35266443, 2022). "We have previously demonstrated that NLRP3 inflammasome is activated in platelets in response to cecal ligation-puncture (CLP) and is associated with multi-organ injury in response to polymicrobial sepsis in a 72 h CLP rat model." (PMID 34638670, 2021). "The inhibition of NLRP3 alleviates the promoting effect of miR-200a-3p on inflammation in sepsis." (PMID 34858199, 2021). "The expression level of NLRP3 in sepsis patients was significantly increased." (PMID 34220338, 2021). "Thus, PTMs of NLRP3, particularly phosphorylation and ubiquitination, regulate its activation and play an important role in sepsis." (PMID 34745104, 2021). "The activation of innate immune receptors by fungi generally follows the same pattern as bacteria, with TLR2, TLR4, TLR9 and NLRP3 being common to the fungi (Aspergillus, Candida and Cryptococcus species) most often associated with COVID-19, ALI/ARDS and sepsis." (PMID 33672738, 2021). "In this study, LBH overexpression decreased the expression of proinflammatory cytokines and NLRP3 inflammasome components in lung tissues of sepsis-induced ALI mouse model, indicating that LBH treatment attenuated the inflammation and NLRP3inflammasome activation in sepsis-induced ALI mice." (PMID 33553423, 2021). "In the present study, we hypothesized that blocking platelet activation with Clopidogrel (CLOP) would decrease NLRP3 inflammasome activation, renal and pulmonary injury in response to polymicrobial sepsis." (PMID 34638670, 2021). "Importantly, DHT possessed a significant therapeutic effect on NLRP3 inflammasome–mediated sepsis in mice." (PMID 34721038, 2021). "Interestingly, the NLRP3 inflammasome inhibitors melatonin and cortistatin showed favourable effects in sepsis‐induced cardiac dysfunction in mice." (PMID 34472725, 2021). "Thus, our results identify the p47phox as an important ROS sensing, anti-oxidant mechanism of GPR43 in phagocytes during of sepsis-induced NLRP3 inflammasome." (PMID 34584017, 2021). "Here, we investigated the role of NLRP3/IL‐1β in sepsis‐induced cardiomyopathy and cardiac atrophy." (PMID 34472725, 2021). "Inhibition of TLR4 and NLRP3 signaling pathways can protect sepsis-induced myocardial inhibition." (PMID 34220338, 2021). "Wang and colleagues reported that dihydromyricetin could alleviate sepsis-induced acute lung injury by inhibiting NLRP3 inflammasome-dependent pyroptosis in mouse models." (PMID 34305952, 2021). "Extracellular histone H3 induced by LPS could cause pyroptosis during sepsis via NOD2 and VSIG4/NLRP3 pathway." (PMID 34906145, 2021). "A mouse sepsis model study showed that H2 inactivates NLRP3 inflammasome and mitochondrial dysfunction; this may represent the impaired release of proinflammatory cytokines." (PMID 34140880, 2021). "These lines of evidence demonstrated a significant role of NLRP3 in sepsis pathophysiology, and blocking NLRP3 may be a promising therapeutic strategy." (PMID 34172780, 2021). "Extracellular histone H3, whose stimulation could elevate the expression of NLRP3 and NOD2, caused pyroptosis in sepsis via NOD2 and VSIG4/NLRP3 pathways." (PMID 34868031, 2021).